HMOX1 (heme oxygenase 1)
Diseases named in the same sentence as HMOX1 in open-access papers (continued):
Sharing a sentence is not in itself a finding about the gene and the disease.
cancer (continued). "The heme oxygenase-1 (HO-1) is an antioxidant protein, which is overexpressed in response to the stress experienced by cancer cells during anticancer therapy for regulating cell apoptosis." (PMID 34206318, 2021). "Single-cell transcriptomic sequencing data were also employed to investigated the role of HMOX1 in cancer cells." (PMID 34858984, 2021). "Recent studies have suggested that heme oxygenase-1 (HO-1) is involved in apoptosis, proliferation and chemoresistance in cancer cells." (PMID 32298237, 2020). "Heme oxygenase-1 (HO-1) is highly induced in various human disease states, including cancer, indicating that HO-1 is an emerging target of cancer therapy." (PMID 32485912, 2020). "Later, we demonstrated that shRNA-mediated genetic inhibition of HMOX1 resulted in diminished viability and proliferation of cancer cells." (PMID 31963199, 2020). "It is important to note that HMOX1 and its metabolic byproducts can be involved in the generation of a permissive microenvironment, which is fundamental for cancer progression." (PMID 32082188, 2020). "Genetic inhibition of HMOX1 by the shRNA approach, although shown to exert an anti-cancer effect, is still far from the therapeutic application." (PMID 31963199, 2020). "Several types of NPs including AgNPs elevate heme oxygenase-1 (HO-1) expression in cancer cell proliferation and angiogenesis." (PMID 32178476, 2020). "It has been recently reported that targets of the Nrf2 gene, such as HMOX1, facilitate cancer development because they counteract the effect of oxidative stress in transformed cells." (PMID 32060354, 2020). "Consistently, the knockout of HMOX1 suppresses, whereas the overexpression of HMOX1 promotes, ferroptotic cancer cell death induced by erastin or BAY 11-7085 (NFKB inhibitor alpha [NFKBIA/IKBA] inhibitor)." (PMID 33117818, 2020). "Downregulation of miR-155 would significantly decrease the cellular levels of Nrf2, NAD(P)H quinone oxidoreductase 1, and heme oxygenase-1 (HO-1), thus suppressing cancer cell survival and migration and facilitating cell apoptosis." (PMID 32411322, 2020). "We then focused on an article that describes the fragment of heme oxygenase 1 cleaved by HsSPP that was transported to the nucleus and enhanced the proliferation and migration of cancer cells." (PMID 32686366, 2020). "In cancer, NRF2-mediated disruption of HMOX-1 and ferritin signaling can impact cancer cell proliferation, angiogenesis, metastasis, and response to therapy, which is usually influenced by the amount of ROS and iron present." (PMID 33080927, 2020). "Heme oxygenase 1 (HO-1) has been reported to be very important in the pathogenesis or progression of multiple types of cancer." (PMID 30606233, 2019). "Over-regulation of Heme oxygenase 1 (HO-1) has been recently identified in many types of human cancer, and in these cases, poor clinical outcomes are normally reported." (PMID 30759842, 2019). "It has been shown that heme oxygenase-1 (HO-1) provides an antioxidant survival mechanism in cancer cells." (PMID 31636810, 2019). "Taken together, these results demonstrate that SEMA6A is a potential suppressor of cancer migration that functions through the NRF2/HMOX1 axis." (PMID 31527696, 2019). "To further study if that down-modulation of NRF2 affects the expression of its target genes we measured in the same system the expressed levels of HMOX1, that normally exerts an important antioxidant effect in cancer cells." (PMID 31905996, 2019). "For improving the understanding of SEMA6A-derived migration pathway, we also determined the mRNA expression levels of PLAU, MMP1 and MMP9 using RT-qPCR, because these genes were indicated to be reduced by HMOX1 and to induce migration in cancer cells." (PMID 31527696, 2019). "Heme oxygenase 1 (HO-1) is crucially involved in cell adaptation to oxidative stress and has been demonstrated to play an important role in cancer progression and resistance to therapies." (PMID 29951371, 2018).
cancer (continued). "The fourth protein was the pro‐angiogenic, anti‐inflammatory, antimetastatic enzyme heme oxygenase 1 (HO‐1 or hsp32), which is overexpressed in many cancers including BC." (PMID 30019538, 2018). "Heme oxygenase 1 (HO-1) is a potential therapeutic target due to its cytoprotective activity in cancer cells." (PMID 30367621, 2018). "In agreement, several studies suggest that, while having cytoprotective functions in untransformed cells, HMOX1 plays a cytotoxic role in cancer cells." (PMID 29755668, 2018). "Curcumin also inhibited angiogenesis through the mediation of angiopoietins 1 and 2, HIF-1, and heme oxygenase 1 (HO-1) in cancer cells." (PMID 29760813, 2018). "RNF139 ubiquitinated and degraded the antioxidant enzyme heme oxygenase-1 (HO-1) and suppressed HO-1-induced cancer cell growth, migration and invasion." (PMID 28662643, 2017). "Heme oxygenase-1 (HO-1), an inducible heme degrading enzyme important for iron hemostasis and oxidative stress response, emerges as a novel target of cancer therapy." (PMID 28978042, 2017). "Nrf2 renders cancer cells resistant to oxidative stress-mediated cell death by activating the transcription of antioxidant genes including HMOX1 and NQO1." (PMID 27764794, 2016). "Heme oxygenase-1 (HO-1) is an enzyme contributing to the development and progression of different cancer types." (PMID 26927195, 2016). "In particular, heme oxygenase 1 (HO-1) exerts a strong antioxidant and antiapoptotic effect favouring cancer cell growth and resistance to therapy." (PMID 26697129, 2016). "One such strategy that we recently identified is to upregulate heme oxygenase 1 (HO-1) in cancer cells (manuscript in preparation)." (PMID 27510263, 2016). "In order to validate these superior and selective cytotoxicities of cpKimchi in cancer cell only, we checked the expression of heme oxygenase-1 (HO-1) after 6 and 18 hr, respectively." (PMID 26317548, 2015). "Heme Oxygenase-1 (HO-1) is expressed in many cancers and promotes growth and survival of neoplastic cells." (PMID 20667089, 2010). "The expression profiles of Hmox1, Pten and E2f7 genes were similarly altered by mastic oil in the majority of test cancer cell lines." (PMID 20003503, 2009). "The cytoprotective enzyme heme oxygenase-1 (HO-1) is significantly overexpressed in PaCa and seems to play an important role in cancer resistance to anticancer treatment." (PMID 19508729, 2009). "Piperlongumine may enhance ROS generation and cell death in cancer cell lines through Nrf2‐mediated mechanisms, as it interacts with Keap1 and increases heme oxygenase 1 production." (PMID 40916076, 2025). "Additionally, HMOX1/HO-1 (heme oxygenase 1), an anti-apoptotic gene, plays a role in regulating autophagy in cancer." (PMID 40851276, 2025). "Investigating the influence of MES on ferroptosis-related genes, especially ATF3, HMOX1 and CDKN1A, may provide valuable insights into the molecular mechanisms underlying its action and offer potential therapeutic strategies for cancer treatment." (PMID 39857803, 2025). "Therefore, HMOX1 is commonly regarded as a survival molecule that plays an important role in cancer progression and can be directly upregulated by the activation of Nrf2." (PMID 40544155, 2025). "Essentially, there’s a beneficial threshold where HMOX1 helps protect cells, but beyond this limit, it may act as an oncogene, promoting cancer development." (PMID 41333220, 2025). "Luteolin significantly inhibited Nrf2 and its target genes [NADPH quinone oxidoreductase 1 (NQO1), heme oxygenase-1 (HO-1), and GSTα1/2] in resistant cells, while the combination of luteolin with different chemotherapeutics demonstrated synergistic effects in anti-cancer activities." (PMID 39061884, 2024).
cancer (continued). "NRF2 is often hyperactivated in MDR cancers, leading to increased expression of antioxidants such as heme oxygenase 1 (HO-1) and NAD(P)H quinone dehydrogenase 1 (NQO1), transporter proteins like multidrug resistance protein 1/2 (MRP1/2), and detoxifying enzymes like glutathione S-transferase (GST)." (PMID 39519053, 2024). "Interestingly, the analysis revealed positive correlations between Hmox1 and a number of established M2 macrophage markers across multiple cancer types." (PMID 37958903, 2023). "Recent studies have demonstrated that activation of c-Met can modulate the redox protective nuclear factor erythroid 2-related factor 2 (Nrf2)/heme oxygenase-1 (HO-1) and downregulate reactive oxygen species (ROS), eventually inhibiting the death of cancer cells." (PMID 36770971, 2023). "Notably, several other NRF2 target genes, such as HMOX1 and NQO1, which are associated with antioxidant activity and ferroptosis, were also downregulated in UTP11-deficient cancer cells." (PMID 37087976, 2023). "Heme oxygenase-1 (HO-1) plays a significant role in protecting against inflammation-induced damage and the accumulation of reactive oxygen species (ROS), particularly in lethal illnesses such as acute autoimmune response, lung conditions, and malignant tumors." (PMID 37239882, 2023). "Cancer cells exposed to several stress factors (hypoxia, reactive oxygen species, cisplatin, and oxidative stress) and Heme oxygenase 1 (HO-1) display a cytoprotective role against oxidative stress and inhibit apoptosis, metastases, angiogenesis, and cell proliferation processes." (PMID 37242590, 2023). "On the contrary, knockdown of MAP3K5, LURAP1L, BNIP3 and HMOX1 enhanced cancer cell migration." (PMID 36899330, 2023). "Furthermore, we observed semaphorin 6A upregulated, and recent research profiled SEMA6A as a suppressor of cancer cell migration via the NRF2/HMOX1 axis." (PMID 37208732, 2023). "Thus, we suppose that the anti-cancer effects of pharmacological VC supplementation are at least partially attributable to HMOX1, which leads to the pharmacological-VC -dependent mTORC1 inactivation." (PMID 36787291, 2023). "Our study found that CLEFMA induced the heme oxygenase-1 (HO-1) level by activating p38 mitogen-activated protein kinase signalling cascade and subsequently activated caspase-dependent cell death, which is critical to the anti-cancer effect in OSCC." (PMID 36428612, 2022). "Our in vivo and in vitro experimental results using the HMOX-1 agonist Hemin support this hypothesis, and the application of HMOX-1 modulators to mediate ferroptosis might be a new strategy for cancer chemotherapy." (PMID 35264971, 2022). "The role of HMOX1 in cancer remains controversial, and further exploration is urgently needed." (PMID 36213835, 2022). "Pan-cancer analyses were performed to investigate the role of HMOX1 in metastasis regulation." (PMID 36033490, 2022). "Increasing evidence has demonstrated the regulatory role of HMOX1 in cancer progression." (PMID 35800617, 2022). "Considering the importance of LDH in cancer metabolism and HO-1-mediated effects on this enzyme transcription and activity in PCa cells, we searched public database repositories and performed a bioinformatics analysis to determine the clinical significance of LDHA, LDHB and HMOX1." (PMID 34208670, 2021). "Biochemical studies showed that Zn(II)–curc treatment increased the NRF2 protein levels along with its targets, heme oxygenase-1 (HO-1) and p62/SQSTM1, while markedly reduced the levels of Keap1 (Kelch-like ECH-associated protein 1), the NRF2 inhibitor, in the cancer cell lines analyzed." (PMID 33669070, 2021). "In the cancer cell lines analyzed, Zinc–curcumin Zn (II)–curc compound can also display anticancer effects via diverse molecular mechanisms, including markedly increasing heme oxygenase-1 (HO-1) p62/SQSTM1and the Nrf2 protein levels along with its targets." (PMID 35011412, 2021).
cancer (continued). "However, the poor correlations between HMOX1 expression and cancer stemness, TMB, and MSI indicated that HMOX1 was unlikely to influence oncogenic processes by engaging in genetic alterations or epigenetic modifications." (PMID 34858984, 2021). "In addition to its affect in cancer models, the inhibition of HMOX1 by ZnPP protects against doxorubicin-induced ferroptotic damage in heart." (PMID 33117818, 2020). "Heme oxygenase-1 (HO-1), an enzyme catalyzing heme degradation, plays important role in regulating oxidative stress, apoptosis, proliferation, angiogenesis and chemoresistance in cancer cells." (PMID 32298237, 2020). "The expression of HMOX-1 was reported to be enhanced in cancer cells." (PMID 31581661, 2019). "However, HMOX-1 overexpression has been observed in a variety of malignancies, and in these settings, it has been found to promote cancer cell survival and proliferation, and the onset of multi-drug resistance." (PMID 31251786, 2019). "We provide evidence that increased HMOX-1 levels in ATL cells may counteract effects of anti-cancer drugs that act by inducing oxidative stress." (PMID 31251786, 2019). "The role of heme oxygenase-1 (HO-1) in cancer biology is poorly understood." (PMID 31163602, 2019). "Furthermore, DK1 also inhibited the anti-apoptosis proteins like HO-1/HMOX1/HSP32 which provide a cytoprotective effect for cancer cells against apoptosis." (PMID 29303982, 2018). "Another aspect of intestinal inflammation where HMOX1 is involved is cancer." (PMID 30258436, 2018). "The importance of NRF2 in mediating interactions between iron and oxygen is becoming apparent as we identify how deregulated NRF2 facilitates iron-mediated cellular pathologies: disruptions to HMOX-1 and ferritin signaling enable cancer progression and reduce treatment efficacies." (PMID 28793787, 2018). "Under the high oxidative stress (treatment with 500μM H2O2), cancer cell viability was reduced by 90% upon silencing of either HMOX1 or TXN, indicating that both antioxidant defense mechanisms have to be intact for cancer cell survival in high oxidative stress conditions." (PMID 29755668, 2018). "It is interesting to note that this effect might be (cancer) cell-specific, since the opposite activity against HMOX1 expression was observed for chlorophyllin-treated human umbilical vein endothelial cells." (PMID 30057678, 2018). "Finally, within the list of upregulated genes in the UCHL1 KD we also found several cancer-associated genes such as SERPINB4, FGF21, NUPR1, SBSN, GDF1, HMOX1, or SOCS2, which suggested the activation of potential compensatory mechanisms in these KDs cells." (PMID 28472177, 2017). "As the hypoxic response and regulation of iron metabolism are tightly interconnected, HIF1A may be involved in regulating genes that maintain iron homeostasis, e.g., transferrin, TFR1, ceruloplasmin, and heme oxygenase 1 in cancer." (PMID 26560875, 2016). "Both Hmox1 and Nrf2 contribute to distant metastasis of cancer." (PMID 27999449, 2016). "The induction of HMOX1 by EENL treatment could be the possible mechanism to attenuate the excess formation of blood vessels in inflammatory angiogenesis of the cancer." (PMID 22461839, 2012). "Thus, high basal GCLC and HMOX1 may support the tumorigenic behavior of cancer cells chronically exposed to IL-1." (PMID 39936983, 2025). "However, the study’s limitations include the lack of in vivo validation of CMSP effects and the sole detection of HMOX1 expression in SCLC cancer tissues and adjacent tissues, necessitating further exploration to elucidate the effects and mechanisms of CMSP in vivo." (PMID 39822985, 2025). "Indeed, it has been reported that sEVs from castration-resistant cancer cells promote the conversion of androgen-sensitive cells into the aggressive hormone-independent phenotype through the activation of heme oxygenase-1 (HMOX1), a rate-limiting enzyme of heme degradation." (PMID 39316264, 2024).
cancer (continued). "Furthermore, inhibition of HMOX1 can also enhance cancer immunotherapy." (PMID 35370706, 2022). "HMOX-1 induction has been highlighted as a mechanism involved in cancer progression, playing a role in cancer growth, metastatic potential, invasiveness, angiogenesis, and resistance to therapies in many cancers, including multiple myeloma, acute leukemia, and neuroblastoma." (PMID 35053476, 2022). "Therefore, HMOX-1 plays a pivotal role in promoting CTX-induced cancer cell ferroptosis." (PMID 35264971, 2022). "Besides, selectively targeting HMOX1 was effective for therapy resistance in various cancers." (PMID 34858984, 2021). "Moreover, the involvement of HMOX1 in physiological angiogenesis in pregnancy and pathological angiogenesis in cancer has been proposed, since both share a necessity for a permissive microenvironment in which cell invasion, cytoprotection, angiogenesis and immune-escape are favored." (PMID 32082188, 2020). "We have demonstrated that both strategies hamper cancer cell viability and self-renewal capacity and confirmed that the concept of synthetically lethal interactions of HMOX1 and FH genes might be an attractive option for the treatment of HLRCC-associated tumors." (PMID 31963199, 2020). "However, there are more and more studies revealing the functional role of HMOX1 in cancer." (PMID 31527696, 2019). "Interestingly, like HMOX-1, TIGAR is implicated in cancer cell-survival and proliferation." (PMID 31251786, 2019). "Additionally, HMOX-1 expression has been reported to be induced in response to chemotherapies and radiotherapies, which may help confer cancer cells with multi-drug resistance." (PMID 31251786, 2019). "Moreover, IGFBP3 was up-regulated by HMOX1, which attenuated migration capability of cancer cells." (PMID 31527696, 2019). "Interestingly, multiple approaches have been used to reduce HMOX-1 expression in different types of cancer, which have, overall, produced a variety of positive effects, such as increases in sensitivity to anticancer drug-induced apoptosis and reductions in proliferation and invasiveness." (PMID 31251786, 2019). "Hmox-1 may increase the metastatic potential of cancer due to its proangiogenic property." (PMID 27999449, 2016). "We also examined the levels of haem oxygenase 1 (HMOX-1, a metabolic enzyme degrading haem-containing proteins and releasing free iron, bilirubin, and carbon monoxide), which ATO is known to increase in cancer cells." (PMID 41188278, 2025). "Our study demonstrates an increase in cellular HMOX1 expression after CMSP intervention, with lower expression in cancer tissues compared to adjacent tissues." (PMID 39822985, 2025). "Regulated NRF2/HMOX1/GPX4 axis and decreasing GSH as a GSH oxidase, which sensitized cancer cells to radiotherapy and immunotherapy." (PMID 40200790, 2025). "No previous studies have explicitly investigated the biological link between PFKFB4 and HMOX1 gene expressions using the GEPIA database, highlighting a gap in the current literature on their combined role in cancer survival outcomes." (PMID 40739397, 2025). "Expression of the HMOX1 gene was markedly increased under CMSP treatment, while lower expression was observed in cancer tissue compared to adjacent tissue." (PMID 39822985, 2025). "To mitigate this, we focused on assessing mRNA levels of key antioxidant enzymes (NFE2L2, HMOX1, SOD2, CAT) in both thyroid normal and cancer cells to gain insight into their oxidative stress response ability." (PMID 40927570, 2025). "KEGG pathway enrichment was performed on 74 target genes using DAVID, and four genes, BMPR2, HMOX1, HNRNPK and ZEB1, were enriched on the “microRNAs in cancer” signal pathway." (PMID 38693503, 2024).